ERBB3 (erb-b2 receptor tyrosine kinase 3)
Diseases named in the same sentence as ERBB3 in open-access papers (continued):
Sharing a sentence is not in itself a finding about the gene and the disease.
tumor (continued). "Furthermore, mir-152-3p negatively regulated ERBB3 by binding to the 3'-UTR of ERBB3, and down-regulation of ERBB3 by small interfering (si)RNAs inhibited proliferation and colony formation of TPC-1 cells, indicating that mir-152-3p acted as an anti-tumor miRNA by negatively regulating ERBB3." (PMID 28570571, 2017). "Additionally, tumor cells within the blood vessels in the omentum also showed high levels of ERBB3." (PMID 29321816, 2017). "Thus, studies on dysregulation of HRG in cancers may improve our understanding of the ligand’s biological function in erbB3-mediated tumor initiation and progression, and facilitate the development of novel strategy for cancer therapy." (PMID 24886126, 2014). "However, tumor cells may eventually develop resistance to the anti-erbB3 Abs, since the Abs like EGFR/erbB2-targeted therapies just inhibit signaling without altering expression of the erbB receptors." (PMID 24886126, 2014). "In our case, although MM-121 itself cannot trigger ADCC, because of its IgG2 isotype, it is possible that inactivation of erbB3 with MM-121 may increase trastuzumab’s binding efficiency to the tumor xenografts-established from BT474-HR20 cells, and subsequently enhance trastuzumab-mediated ADCC." (PMID 24215614, 2013). "Finally, we wanted to determine if targeted ErbB3 inhibition could effectively prevent tumour cell proliferation and downstream signalling in PDAC." (PMID 21792199, 2011). "However, it remains to be established whether BCAR4-positive primary tumours have elevated levels of phosphorylated ERBB2 or ERBB3." (PMID 20859285, 2010). "In particular, this hypothesis is supported by the in vitro targeting experiments showing that ALM is capable of selectively binding ErbB2‘+’/ErbB3‘+’ tumour cells when present in a milieu of cells that express either elevated levels of one or normal levels of both target antigens." (PMID 18841159, 2008). "In summary, we present the diverse landscape of ERBB2/ERBB3 activating alterations and co-alterations across >500,000 solid tumors which has implications for HER2/3-targeted therapies pan-tumor." (PMID 40178042, 2025). "The group generated circulating tumour cell organoids from patients and identified neuregulin 1 (NRG1)-ERBB2 receptor tyrosine kinase 3 (ERBB3/HER3) signalling as a key survival pathway for cells through multiomics." (PMID 40650785, 2025). "Among them, seven cancer genes (ERBB2, ERBB3, PPARG, MYC, CCND1, CCNE1, MDM2) were detected to be amplified in both ctDNA and tumor tissues, indicating the reliability of ctDNA in reflecting the genomic features of tumors." (PMID 40191434, 2025). "For instance, Listeria monocytogenes and F. nucleatum can activate RTKs like ErbB2, ErbB3, and EGFR, promoting tumor growth and resistance to RTK-targeted therapies in CRC." (PMID 39948481, 2025). "Examining tumor samples by IHC, D1SP-treated tumors had lower percentages of Ki-67+ cells and less protein expression of p-ErbB3, p-ErbB2, and p-cMet compared with control tumors." (PMID 39748059, 2025). "Previous research has shown that HOXC10 is overexpressed in numerous tumors, where it promotes tumor cell proliferation through the activation of signaling pathways such as the MAPK and ERBB3/PI3K/AKT axes." (PMID 41268215, 2025). "Epidermal growth factor receptor (EGFR/ErbB1/HER1) and other members of the ErbB family, including ErbB2/HER2, ErbB3/HER3, and ErbB4/HER4, are receptor tyrosine kinases that play critical roles in tumor progression across various types of cancer." (PMID 40445424, 2025).
tumor (continued). "We sought to define the pan-tumor landscape of activating ERBB2 and ERBB3 genomic alterations detected by comprehensive genomic profiling (CGP)." (PMID 40178042, 2025). "More encouraging are the recently developed anti-ERBB/ERBB2/ERBB3 targeted therapies for the treatment of carcinomas harboring NRG1 fusions, as would be considered for our patient if her tumor were to eventually recur." (PMID 39575425, 2024). "It has been discovered that the over-activation of the EGFR family of RTK, which includes EGFR (EGFR/HER-1 or ERBB-1), HER-2 (Neu or ERBB-2), HER-3 (ERBB-3), and HER-4 (ERBB-4), promotes the growth and progression of numerous tumor types." (PMID 39130630, 2024). "This tumor suppressor miRNA has other targets such as ERBB2, ERBB3 and cytochrome P450 family 24 subfamily A member 1 (CYP24)." (PMID 38954129, 2024). "Conversely, ERBB3 expression was limited to cells derived from the VMT, primarily observed in the tumor population." (PMID 38183074, 2024). "Drugs targeting the binding of NRG1 to ERBB3 and/or the heterodimerization of ERBB2/ERBB3, such as the bispecific monoclonal antibody zenocutuzumab, have demonstrated tumor volume reduction inNRG1fusion-positive tumors." (PMID 38414979, 2024). "The analysis revealed that ERBB3 signaling was exclusively present in the VMT dataset, with fibroblasts and tumors acting as ligand sources for the receptor on the tumor population." (PMID 38183074, 2024). "In this cohort, one patient displayed strong ERBB3 and two patients displayed strong ERBB4 upregulation in the relapsed tumor compared to the primary tumor." (PMID 36181342, 2023). "All four members of this family, including HER1 (EGFR, ErbB1), HER2 (Neu, ErbB2), HER3 (ErbB3), and HER4 (ErbB4), play an important role in cell growth regulation, proliferation, and tumor migration." (PMID 39355049, 2023). "The anti-ErbB3 mAb, CDX-3379, previously demonstrated encouraging albeit preliminary anti-tumor activity in HPV-negative HNSCC." (PMID 35625959, 2022). "In an attempt to elucidate the molecular mechanism (s) by which ERK3 overexpression promotes tumor development, we examined the effects of ERK3 overexpression on the activating phosphorylations of ERBB1, ERBB2, and ERBB3." (PMID 34719109, 2022). "Specifically, in magenta, a subset of neural crest progenitor markers, such as NES, SOX10, ERBB3, and NGFR, were reported as highly expressed markers of Schwann cell progenitors and the signatures of stem-like tumor cells in NF1 tumors." (PMID 35741605, 2022). "With IPMN progression, tumor stemness increased continuously, and KRAS, ERBB3, RUNX1, and ELF3 are essential driver genes affecting tumor stemness." (PMID 36090038, 2022). "We first compared the expression pattern of EGFR, ERBB2, ERBB3, ERBB4 in CESC tumor and normal tissues." (PMID 35581263, 2022). "Western blot analyses showed that infigratinib-resistant HCC21-0208, HCC06-0606, and HCC01-0909 tumours constitutively express higher levels of p-EGFR, p-ErbB2, and p-ErbB3." (PMID 34156519, 2021). "Epidermal growth factor receptor 3 (ERBB3) is a surface tyrosine kinase receptor belonging to the EGFR/ERBB family, involved in tumor development and progression." (PMID 33799723, 2021). "The results of protein interaction analysis in Pathway Common also showed that MAPK upstream kinases (MAP3K3, MAP3K5), ERBB3 and ULK1, which are important for tumor cell growth and proliferation, can bind to NEDD4L." (PMID 34539897, 2021). "ERBB3 is the only member of the ERBB family that lacks intrinsic kinase activity, although evidence shows that tumor phenotypes can be modulated by activation of ERBB3-dependent pathways." (PMID 34843459, 2021). "Apart from KRAS and PIK3CA, other genes preferentially altered in the right-sided primary tumor sites, such as PRKDC, ERBB3, BCLAF1 and NOTCH1, have been reported to be correlated with poor prognosis or migration in CRC." (PMID 34281583, 2021).
tumor (continued). "Although the overexpression of NRG1 and ERBB3 drastically increases the serum levels of PARK7 and in vivo tumor formation, it markedly reduces the intratumoral expression of PARK7." (PMID 32357493, 2020). "We further showed that the ErbB3-suppressive and CD8+ T-cell–inflamed tumor microenvironments of MAPK pathway mutant HNSCC tumors are likely two independent molecular characteristics of MAPK-mutated HNSCC patients with remarkably improved outcomes." (PMID 32381551, 2020). "Together, these data indicate that DFTD tumor cells, which express high levels of phosphorylated ERBB2 and ERBB3 and show activation of the ERBB signaling pathway, are exquisitely vulnerable to ERBB kinase inhibitors." (PMID 30645971, 2019). "The human epidermal growth factor receptor family consists of four members: EGFR (HER1, erbB1), HER2 (erbB2, neu), HER3 (erbB3) and HER4 (erbB4), all of which regulate the proliferation and differentiation of various tumour cells." (PMID 30858756, 2019). "Seventeen, 19, 20, and 20 out of 20 ErbB3 over expressed cases were infiltrative, poorly differentiated, stage of III/IV, and with a positive tumor relapse (p < 0.05), respectively." (PMID 30621788, 2019). "Activation of the NTSR1 receptor leads to activation of the EGFR family: in particular EGFR, ErbB2/HER2, and ErbB3/HER3, which in turn are responsible for signal transduction within the tumor cell." (PMID 29467963, 2018). "This led to a model for macrophage-enhanced iTEM in which NRG1 produced by tumor cells binds to ErbB3 on macrophages and induces expression of JAG1, which in turn enhances tumor cell intravasation." (PMID 29636067, 2018). "Large cohorts of patients, multi histology basket trials or tumor agnostic meta-analysis would be required to clarify the algorithm of treatment decision in case of ERBB2 and ERBB3 alterations, based on previous preclinical and clinical data available." (PMID 29515767, 2018). "These heavily pre-treated patients received the combination of lumretuzumab, a monoclonal anti-ErbB3 antibody, plus erlotinib, an anti-EGFR small molecule, showing tumor shrinkage." (PMID 29515761, 2018). "No tumors had very high simultaneous EGFR and ERBB2 protein expression (IHC Tumor Cell Score ≥ 2.5), while one Uro tumor had high EGFR and ERBB3 protein expression." (PMID 28388586, 2017). "Our data demonstrate that overexpression of HCaRG inhibits RCC development and tumor angiogenesis by inactivating the proto-oncogene, ErbB2, and gene silencing of EGFR and ErbB3." (PMID 29050225, 2017). "In this report, we show that dual ErbB blockade through the combination of cetuximab with the anti-ErbB3 antibody KTN3379, resulted in improved anti-tumor activity relative to either agent alone." (PMID 28723928, 2017). "In conclusion, our preclinical data in HNSCC provide both a unique view of EGFR, HER2, and ErbB3 signaling and a mechanistic rationale to combine EGFR and ErbB3-targeting therapies for the treatment of this tumor type." (PMID 28723928, 2017). "When examining consistently altered pathways or kinases across more than one platform, the GNRH, PTEN, STAT3, IL-8, B cell receptor, NF-kB and NO-ROS in macrophages pathways as well as the kinases ERBB2, ERBB3 and SYK were upregulated in tumor tissue." (PMID 28423512, 2017). "We previously demonstrated that nectin-like molecule-2 (Necl-2)/cell adhesion molecule 1 cis-interacts with ErbB3 via the extracellular region and with the protein tyrosine phosphatase PTPN13, a tumour suppressor, via the cytoplasmic region." (PMID 28900130, 2017). "Examining the very high expressing cases (with Tumor Cell Score ≥ 2.5, indicating high protein expression throughout the tumor), EGFR+ERBB2 expression was only observed in one GU tumor, while two UroA tumors expressed both EGFR and ERBB3 at high levels." (PMID 28388586, 2017).
tumor (continued). "Due to its ability to interfere with tyrosine-phosphorylation of ErbB2 and ErbB3, EGCG further inhibited downstream MAPK cascade, leading to the reduction in tumor growth." (PMID 28286519, 2017). "The ErbB family of RTKs, which consist of Epidermal growth factor receptor (EGFR) (ErbB1 or HER1), ErbB2 (HER2 or Neu), ErbB3 (HER3), and ErbB4 (HER4), have been shown to promote tumor progression in various cancer types." (PMID 27902463, 2017). "Dual targeting of EGFR and ErbB3 most effectively blocked p-Erk and p-Akt in the presence of EGFR ligands and HRG, which translated into synergistic inhibition of tumor growth in A549 and H322." (PMID 28725482, 2017). "The top 10 unpaired normal (n=4 samples) to tumor (n=11 samples) increased protein kinases were SYK, ZAP70, ARG (ABL2), ERBB3, ABL, TEC, MER (MERTK), AXL, EGFR and ERBB2." (PMID 28423512, 2017). "Here, we explore the anti-tumor activity of KTN3379 (also known as CDX-3379) in HNSCC and evaluate dual ErbB3/EGFR blockade with KTN3379 and cetuximab." (PMID 28723928, 2017). "Although ERBB3 lacks a kinase domain, ERBB3 dimerize with ERBB2 which activates PI3K/AKT, MEK/MAPK, and JAK/STAT signaling cascades for tumor initiation and progression." (PMID 29321816, 2017). "ERBB3 IHC on average revealed moderate to strong expression in 75% of cells in both primary and secondary DFT1 tumours in cytogenetically determined strains 1 to 5 of DFT1." (PMID 28591206, 2017). "In contrast, the sustained inhibition of AKT seems to be the prerequisite for eliciting apoptosis in ErbB2-overexpressing tumours and signifies the importance of preventing the p-AKT rebound for the potency of anti-ErbB2/ErbB3-targeting agents." (PMID 27255951, 2016). "In the present study we demonstrated for the first time the synergistic antitumor effect between a HDACi, such as vorinostat or VPA, and the anti-ErbB3 MoAb A3, in a set of NSCLC primary tumor cultures." (PMID 26862736, 2016). "Increased expression of ErbB3 in CRC was found to correlate with poorer overall survival and disease stage and as revealed in this study with higher tumor grade." (PMID 27447549, 2016). "Negative methylation/expression correlations were also found for HDAC4 (a chromatin modifier), ERBB3 (a known oncogene), as well as MARCKS and CXCR4; genes known to induce tumor cell invasion and therapeutic resistance in other tumor types." (PMID 26963385, 2016). "ERBB2 and ERBB3 dimerization triggers the activation of survival and growth signaling cascades, such as through PI3K and MAPK kinases, in both normal and tumor cells." (PMID 27626312, 2016). "Nuclear ErbB3 expression was most often observed in CRPC (17/ 32, 53%) than in HS tumours (43/ 137, 31%) (p = 0.03, Chi 2 test)." (PMID 27191720, 2016). "Consistently, both the upregulation of ErbB3 mRNA and the concentration of NRG-1 in tumor predict trastuzumab drug resistance." (PMID 27596216, 2016). "Using a 3D CRC cell culture model, we here show for the first time that K-RasG12V induced hyperproliferation and loss of polarized morphogenesis, both of which are hallmarks of tumor progression, engage a HRG/ErbB3 dependent signaling loop." (PMID 27447549, 2016). "By indirect immunofluorescence, ErbB3 staining was mainly present at the plasma membrane and in the cytoplasm of RWPE cells whereas a high nuclear staining was detected in tumour cell lines." (PMID 27191720, 2016). "A closer look at the data revealed that parental tumors and PDGCX models agreed well for both protein biomarkers, when the parental tumor was positive for the biomarker (14/16 for ERBB1 and 22/27 for ERBB3)." (PMID 26217940, 2015). "NRG-1β, the predominant ErbB-3 ligand, has been shown to be released in the tumor microenvironment by stromal cells and to promote CRC progression through ErbB-3 mediated PI3K/AKT activation." (PMID 26160848, 2015). "For example, EZN3920 is an ErbB3-directed LNA-ASO which potently inhibits growth and survival of HER2+ tumor cells both in vitro and in vivo." (PMID 26637440, 2015).
tumor (continued). "The localisation of ERBB3, EPHB2 and KI-67 within tumours was investigated using co-immunofluorescence." (PMID 26367378, 2015). "Activation or overexpression of ErbB such as ErbB2 (HER2) and ErbB3 (HER3) and EGFR has been observed in various types of tumours." (PMID 25977926, 2015). "ERBB3 is also unique among the ErbB family in its ability to directly recruit and activate the PI3K/Akt signaling pathway, which undoubtedly favors tumor growth and progression." (PMID 25248370, 2014). "Epidermal growth factor receptor belongs to the ErbB family of tyrosine kinase receptors, which includes EGFR (ErbB-1), HER-2/neu (ErbB-2), HER-3 (ErbB-3), and HER-4 (ErbB-4), all known to be involved in modulating pathways of tumor growth or proliferation." (PMID 24945674, 2014). "MCF-7 cells (1 × 107 cells per 0.1 mL) with elevated miR-143/145 or ERBB3 levels were implanted subcutaneously into 4-week-old C57/BL6 mice, and tumor growth was then evaluated at day 28 after cell implantation." (PMID 25248370, 2014). "We compared the expression of Erbb3 in tumors from control and MARKO mice to non-tumor bearing mammary glands." (PMID 23593223, 2013). "A similar phenomenon has been described for other RTKs such as EGFR, ErbB2, ErbB3, ErbB4 and VEGFR2 where truncated versions had functional implications for the growth of the tumor cells." (PMID 24205204, 2013). "As expected, the ERBB3 gene and networks partners were significantly enriched in GNB and GN tumours compared to NB." (PMID 23835063, 2013). "MM-121 inhibits HRG-1-induced ErbB3 and AKT phosphorylation with IC50 values of 2.4 and 6.0 nM respectively and completely inhibits in vivo tumor xenografts of renal ACHN cells." (PMID 22889873, 2012). "Several candidate genes, such as MYCN, ERBB3, JUN, and IGFBP5, were also significantly upregulated, which keeps the tumor in a proliferative state." (PMID 22690114, 2012). "All together these findings suggest that ErbB3 cooperates with HER2 to induce changes in breast epithelium before, during and after tumor formation." (PMID 22889873, 2012). "Further, we determined binding of CL4 on stable tumor derived cell lines that differently express EGFR family members (EGFR, ErbB2, ErbB3, or ErbB4)." (PMID 21915281, 2011). "In advanced tumours, EGFR, ERBB2 and ERBB3 upregulation is common and there is a relationship between expression of ERBB2 and ERBB3 but not the NRG1 ligand." (PMID 21364580, 2011). "For example, ErbB2 and ErbB3 cooperate to promote MMTV-Neu induced tumorigenesis, and activation of AKT and MAPK downstream of ErbB2/ErbB3 affects tumor cell proliferation." (PMID 20860838, 2010). "To model the effects of ErbB2‘+’/ErbB3‘+’ normal tissue on ALM targeting, we used fluorescently labelled MCF10a normal breast epithelial cells mixed with unlabelled BT-474 tumour cells." (PMID 18841159, 2008). "Increased levels of ErbB3, Tyr1289-phosphorylated ErbB3, epidermal growth factor receptor (EGFR) and ErbB4 were readily detected in the c-ErbB2 tumours compared with normal tissue from the same mice." (PMID 18700973, 2008). "c-ErbB2 tumours demonstrate overexpression of EGFR, ErbB2, ErbB3 and ErbB4, and activation/phosphorylation of both ErbB2 and ErbB3, underscoring the importance of the entire EGFR family in ErbB2-induced tumourigenesis." (PMID 18700973, 2008). "These CAR-NK cells demonstrated high cytotoxicity against ErbB3-positive tumor cells and significantly reduced tumor size in animal models, without observable side effects." (PMID 40299429, 2025). "Amongst these are notable tumor related genes AKT3, CDKN1A, ESR1, FOXO1, TSC2, ERBB3, and NRG4." (PMID 40522948, 2025). "In HM tumours, the antigen-presenting genes HLA-B (26%), HLA-A (25%) and TAP2 (24%) had the highest LOH frequency, whereas TRPS1 (26%), ACVR1B (22%), CYP7B1 (22%), MBD6 (22%) and ERBB3 (22%) had the highest frequency of gains." (PMID 39112715, 2024).